HSF4 (heat shock transcription factor 4)
Description:
Heat-shock transcription factor that specifically binds heat shock promoter elements (HSE). Required for denucleation and organelle rupture and degradation that occur during eye lens terminal differentiation, when fiber cells that compose the lens degrade all membrane-bound organelles in order to provide lens with transparency to allow the passage of light (By similarity). In this process, may regulate denucleation of lens fiber cells in part by activating DNASE2B transcription (By similarity). May be involved in DNA repair through the transcriptional regulation of RAD51. In the eye lens, controls the expression of alpha-crystallin B chain/CRYAB and consequently may be involved in the regulation of lysosomal acidification (By similarity). [Isoform HSF4A]: Transcriptional repressor. [Isoform HSF4B]: Transcriptional activator.
Synonyms: CTM; CTRCT5
Tractability: PROTAC: UniProt records ubiquitination sites on it; ubiquitination databases record sites on it.
Gene: Protein-coding gene on chromosome 16 (67,164,681 to 67,169,945, forward strand). Ensembl gene ENSG00000102878.
Subcellular location: Nucleus
Subcellular location (Human Protein Atlas): Nuclear speckles
Gene Ontology:
Molecular function: DNA-binding transcription factor activity, RNA polymerase II-specific; RNA polymerase II cis-regulatory region sequence-specific DNA binding; sequence-specific double-stranded DNA binding; DNA-binding transcription factor activity; identical protein binding; sequence-specific DNA binding
Biological process: negative regulation of transcription by RNA polymerase II; lens fiber cell differentiation; regulation of transcription by RNA polymerase II; negative regulation of DNA-templated transcription; regulation of DNA-templated transcription
Cellular component: chromatin; nuclear speck; nucleus
Genetic constraint (gnomAD): Loss-of-function variants: 43 observed, 49.92 expected, observed/expected ratio (o/e) 0.86, 90% interval 0.67 to 1.11. The upper end of that interval is the gene's LOEUF score, 1.11, which puts it in group 4 of 6, group 1 being the genes least tolerant of losing a copy. Missense variants: 610 observed, 642.83 expected, observed/expected ratio (o/e) 0.95, 90% interval 0.89 to 1.01. Synonymous variants: 285 observed, 263.79 expected, observed/expected ratio (o/e) 1.08, 90% interval 0.98 to 1.19.
Homologues: Orthologues: chimpanzee HSF4 (99% identical), rabbit HSF4 (95% identical), dog HSF4 (92% identical), macaque HSF4 (92% identical), pig HSF4 (91% identical), guinea pig HSF4 (90% identical), mouse Hsf4 (87% identical), rat Hsf4 (87% identical), tropical clawed frog hsf4 (46% identical), zebrafish hsf4 (31% identical), Caenorhabditis elegans hsf-1 (27% identical), Drosophila melanogaster Hsf (26% identical). Paralogues in human: HSF1 (38% identical), HSF2 (33% identical), HSF5 (15% identical), HSFY1 (14% identical), HSFY2 (14% identical), HSFX1 (12% identical), HSFX2 (12% identical), HSFX4 (11% identical), HSFX3 (11% identical).
Diseases named in the same sentence as HSF4 in open-access papers:
HSF4 is named in the same sentence as 50 diseases in open-access papers, as found by Europe PMC text mining. Sharing a sentence is not in itself a finding about the gene and the disease. The quoted sentences say what the papers report.
cataract (35 papers, 2008 to 2026). Partial or complete opacity of the crystalline lens of one or both eyes that decreases visual acuity and eventually results in blindness. "By contrast, HSF4 is primarily known for its involvement in tissue development, especially associated with cataracts, as demonstrated in multiple studies." (PMID 40004241, 2025). "Mutations in the HSF4 gene cause a recessive form of cataract in Staffordshire bull terriers and Boston terriers, a dominant form of cataract in Australian Shepherds, as well as several forms of cataracts in humans." (PMID 37118843, 2023). "Mutations in the human HSF4 gene have been reported in both autosomal dominant and recessive cataracts, as well as having been associated with age-related cataracts." (PMID 36670602, 2022). "Mutations in the HSF4 gene have been shown to cause cataracts in humans and other mammals, including the recent discovery of a novel HSF4 mutation in pandas." (PMID 34706646, 2021). "The expression of Dnase2b is regulated by lens-specific heat shock transcription factor 4 (HSF4), the deficiency of which in mice caused cataracts and SNPs in humans were linked to cataractogenesis." (PMID 33717156, 2021). "In conclusion, here, we report a novel missense mutation in HSF4 responsible for autosomal recessive congenital cataracts in a large consanguineous familial case." (PMID 31815953, 2019). "Taken together, these results strongly suggest that mutation in HSF4 is responsible for recessive congenital cataracts in PKCC074." (PMID 31815953, 2019). "Mutations in the human HSF4 gene have been reported in both autosomal dominant and recessive cataracts." (PMID 30143024, 2018). "In summary, we have shown a novel missense mutation in HSF4 that mapped to 16q21-22 and caused autosomal-dominant cataracts in a large Chinese family." (PMID 24637349, 2014). "Despite the large number of breeds affected by HC only a single gene, the transcription factor HSF4, has been implicated in the development of cataracts in dogs to date." (PMID 26401320, 2014). "To-date, only eight different mutations in HSF4 have been reported, three of them are causing autosomal dominant cataracts, three are causing autosomal recessive cataracts, and two mutations were found in sporadic cases." (PMID 19014451, 2008). "As a conclusion, we have shown the first nonsense mutation in HSF4 causing autosomal recessive cataracts in a large consanguineous family from Pakistan." (PMID 19014451, 2008). "We identified five new HSF4 mutations in 150 age-related cataract patients, enlarging the spectrum of HSF4 mutations in cataract patients." (PMID 18941546, 2008). "Mutations of HSF4 were associated with autosomal dominant cataracts." (PMID 36824022, 2023). "HSF4’s Alterations are also strongly linked to cataracts, cancer, and other illnesses." (PMID 36681801, 2023). "To date, twenty-seven mutations of HSF4 gene have been reported to cause cataracts." (PMID 36670602, 2022). "The novel missense mutation in the HSF4 gene therefore provides a potential new genetic determinant that could help to predict the risk of cataracts in giant pandas." (PMID 33686159, 2021). "In addition, the same group also analyzed a Danish family whose members were affected with congenital cataracts, as well as in sporadic cataract diseases, and found other missense mutations at the HSF4 DBD." (PMID 33807297, 2021). "We identified a novel missense mutation in HSF4 affecting a female giant panda whose cataracts began to form at 28 years of age which was absent from 13 unaffected controls but present in another panda with cataracts." (PMID 33686159, 2021). "It is therefore clear that mutations affecting the surface topography and intramolecular chain interactions within the HSF4 protein are associated with cataract disease, and we propose that the novel R377W mutation is likely to elicit a similar mechanism in giant pandas." (PMID 33686159, 2021).
cataract (continued). "Moreover, due to HSF4 roles in regulating these important cellular processes, HSF4 genetic alterations or aberrant activities have also been implicated in diseases such as cataracts and cancer." (PMID 33807297, 2021). "Hsf4- knockout mice (Hsf4−/−) and Tdrd7-homozygous KO mice (Tdrd7−/−) also cause cataracts." (PMID 33204712, 2020). "Our report extends the spectrum of HSF4 mutations and may be helpful for the genetic diagnosis of congenital cataracts in the era of precision medicine." (PMID 30143024, 2018). "It has been also reported that Hsf4 mutations may also be associated with age-related cataract and mutations in the DNA binding domain (A20D, I87V, L115P, R120C and R74H) of Hsf4 cause autosomal dominant cataract." (PMID 26187041, 2015). "Despite this, this novel mutation in the HSF4 gene could provide some clues to the mechanism of developing congenital cataracts." (PMID 24637349, 2014). "It is highly likely that other mutations associated with the development of cataracts are co-segregating in the Australian Shepherd population because not all the dogs with bilateral posterior polar subcapsular cataract carried a copy of the HSF4 deletion." (PMID 26401320, 2014). "Mutations in HSF4 were first reported to be related with human autosomal dominant lamellar and Marner cataracts in 2002, and the T→C transition at nucleotide 348 in HSF4 was discovered in the affected individuals of a large Chinese congenital cataract family." (PMID 22509099, 2012). "In humans, missense mutations in the HSF4 gene cause cataracts." (PMID 22509099, 2012). "Apart from autosomal dominant cataracts, mutations in HSF4 may also result in autosomal recessive cataracts." (PMID 22509099, 2012). "It will be important in the future to examine the direct phenotypic consequences of HSF4-loss as well as the contribution of genetic background, epigenetic factors, and environmental factors for the onset and progression of Hsf4 associated cataracts." (PMID 22162625, 2011). "HSF4 knockout mice had abnormal lens development and the formation of cataracts due to aberrant cellular proliferation and differentiation, partly due to the reduced γ-crystallin expression in the lens fiber cells." (PMID 33807297, 2021). "In addition, regarding the clinical phenotype caused by mutations in this transcription factor, the reason that mutations in HSF4 that are expressed in other tissues, including the heart, muscle, lung, and brain, cause only nonsyndromic cataracts is still unknown." (PMID 24637349, 2014). "Targeted deletion of Hsf4 in mice results in cataracts, confirming a critical role of HSF4 for normal lens function." (PMID 22162625, 2011). "Insertion of an early transposable element (ETn) in intron 9 of heat shock factor 4 (Hsf4) was previously identified as responsible for lop11 cataracts." (PMID 22162625, 2011). "This is supported by the fact that heat shock factor 4 (Hsf4) KO mice develop cataracts during the early postnatal period and that Hsp25 gene expression level is decreased several hundred fold in Hsf4 KO mice." (PMID 20104256, 2010). "It has a unique role in the development of the lens at the late embryonic and postnatal stages of mouse development; specifically, disruption of the Hsf4 gene leads to cataracts via multiple pathways." (PMID 19224648, 2009). "Genetic linkage analysis was performed for the common known autosomal recessive cataracts loci and linkage to a locus containing HSF4 (OMIM 602438) was found." (PMID 19014451, 2008).
cataract (continued). "Although the role of the four studied genes: PAX6, PITX3, HSF4 and LIM2 in both ocular and central nervous system development, we report the absence of mutations in all studied genes in four families with phenotypes associating cataract, MR and microcephaly." (PMID 22103961, 2011). "Finally, variations in at least eight genes underlying genetic forms of cataract (EPHA2, GJA8, GALT, SLC16A12, HSF4, GALK1, FTL, and CRYAA), and at least 10 other diverse genes have been associated to varying degrees with age-related cataract." (PMID 21042563, 2010). "Under slit-lamp detection, we observed a cataract phenotype in the Hsf4 knockout mouse." (PMID 19224648, 2009). "Two previously identified mutations (p.Arg175Pro and c.595_599delGGGcc) in Pakistani families showed recessive cataracts and are located in the HR-A and HR-B domains of the HSF4 protein again demonstrating the extreme genetic heterogeneity of the Pakistani population." (PMID 19014451, 2008). "Moreover, common mutations associated with cataracts of various morphologies include genes encoding crystallins (CRYA, CRYB, and CRYG), lens specific connexins (Cx43, Cx46, and Cx50), major intrinsic protein (MIP) or aquaporin, heat shock transcription factor 4 (HSF4), etc. but PAX6 is neglected." (PMID 36843716, 2023). "Additionally, Hsf4, Tdrd7, gap junction protein epsilon 1 (Gje1), beaded filament structural protein 2 (Bfsp2), and lens intrinsic membrane protein 2 (Lim2) which are also significantly reduced in the SCR lens (<0.5-fold) were linked to human or animal cataracts (Supplement 1)." (PMID 33204712, 2020). "Heat shock transcription factor 4 (HSF4) is related with human autosomal dominant lamellar and Marner cataracts; a T→C transition at nucleotide 348 was found in a large Chinese cataract family." (PMID 22509099, 2012).
congenital cataracts (18 papers, 2008 to 2025). "HSF4 is best known for being a crucial developmental factor in the eye, and mutations affecting the activity of HSF4 are linked to the occurrence of congenital cataracts in humans." (PMID 40457168, 2025). "A previous study on a cohort of patients with congenital cataracts in China has indicated that disease development is closely associated with genetic mutations in HSF4 DBD." (PMID 36681801, 2023). "This study aimed to identify the HSF4 mutations in a cohort from Chinese families affected with congenital cataracts." (PMID 30143024, 2018). "HSF4 mutations are responsible for 11.9% (five out of 42) of the families with congenital cataracts in our cohort." (PMID 30143024, 2018). "In the study, we identified five novel HSF4 mutations in Chinese families with congenital cataracts." (PMID 30143024, 2018). "Mutations in the HSF4 were responsible for 11.90% Chinese families with congenital cataracts in our cohort." (PMID 30143024, 2018). "HSF4 was identified as a novel cataractogenic transcription regulatory factor whose mutation was closely associated with congenital cataracts in humans and animals." (PMID 22509099, 2012). "Some transcription factor genes associated with congenital cataracts have been identified, including heat shock transcription factor 4 (HSF4)." (PMID 22509099, 2012). "Mutations in HSF4 have been identified in families with both autosomal dominant and recessive forms of hereditary congenital cataracts." (PMID 22162625, 2011). "HSF4 gene (Heat-shock transcription factor 4) localized on 16q21-q22.1 and for which mutations are associated with both autosomal dominant and autosomal recessive congenital cataract (ARCC)." (PMID 22103961, 2011). "The association of the HSF4 gene with two different modes of inheritance for congenital cataracts can at least in part be explained by the location and severity of the mutations." (PMID 19014451, 2008). "Additionally, cytoskeletal proteins and transcription factors, including Forkhead box protein E3 (FOXE3) and heat shock transcription factor 4 (HSF4), are associated with congenital cataracts." (PMID 40585754, 2025). "Although congenital cataracts associated with HSF4 mutations were initially identified as autosomal dominant traits, others are autosomal recessive, indicating that different types of mutation may have different effects on cataract development." (PMID 33686159, 2021). "Our results expand the spectrum of HSF4 mutations causing congenital cataracts, which may be helpful for the molecular diagnosis of congenital cataracts in the era of precision medicine." (PMID 30143024, 2018). "In humans, four different mutations in HSF4 result in autosomal recessive congenital cataracts." (PMID 22162625, 2011). "In this study, 42 unrelated families with congenital cataracts were recruited from Southeast China, and five mutations in the HSF4 (MIM# 602438, heat shock transcription factor 4) cause congenital cataracts were reported." (PMID 30143024, 2018). "In total, five mutations were identified respectively using directly sequencing of the exons and flanking splicing sites of HSF4, in five unrelated families with congenital cataracts." (PMID 30143024, 2018). "There were no pathological mutations in known genes associated with non-syndromic congenital cataracts, like CRYB, CRYG, Cx43, Cx46, Cx50, MIP, PITX3, MAF, HSF4, and so on." (PMID 28076398, 2017). "Mutations in the heat-shock transcription factor 4 gene (HSF4; MIM: 602438) may result in both autosomal dominant and autosomal recessive congenital cataracts." (PMID 20406438, 2010). "Although several transcription factors such as Pax6, PITX3, HSF4, and HMX1 were allelic with congenital cataracts, MAF family genes are well characterized for the indispensable transcription factor regulating lens development." (PMID 27631609, 2016).
autosomal dominant cataract (10 papers, 2008 to 2023). A syndromic cataract that has autosomal dominant inheritance. "In summary, we identified five novel mutations in HSF4 causing autosomal dominant congenital cataracts in Chinese families." (PMID 30143024, 2018). "Overall, we report four novel mutations in HSF4, CRYGA, CRYGC and PAX6, and one previously reported mutation in GJA3 that cause autosomal dominant congenital cataracts." (PMID 36670602, 2022). "We identified a mutation in exon 10 of the HSF4 gene encoding heat shock transcription factor 4 (HSF4), a protein associated with several forms of autosomal dominant congenital cataract in humans that has also been implicated as a cause of age-related cataracts." (PMID 33686159, 2021).
Age-related cataract (8 papers, 2008 to 2022). A type of cataract (opacification of the lens) that forms during the course of aging. "Overall, the identification of these HSF4 genetic alterations and their associations with both congenital- and age-related cataracts further corroborated the HSF4 indispensable functions in governing normal lens development during eye organogenesis." (PMID 33807297, 2021). "Studies of heat shock transcription factor 4 have revealed two intronic mutations (c.1020–25G>A/ c.1256+25C>T) in patients with age-related cataracts." (PMID 23288985, 2012). "It has been reported that Hsf4 mutation causes human congenital and age-related cataracts." (PMID 33204712, 2020). "Certain sequence changes of HSF4 will permit abnormal expression of HSPs and thereby influence the function or level of HSPs, which might increase the susceptibility to age-related cataract." (PMID 18941546, 2008). "At least 8 genes are known to be directly associated with age-related cataracts, including EPHA2, GJA8, GALT, SLC16A12, HSF4, GALK1, FTL, and CRYAA." (PMID 36107580, 2022). "In this study, we explore the role of HSF4 in the development of age-related cataract." (PMID 18941546, 2008).